CCR4 (C-C motif chemokine receptor 4)
Diseases named in the same sentence as CCR4 in open-access papers (continued):
Sharing a sentence is not in itself a finding about the gene and the disease.
tumor (continued). "Six weeks after tumor implantation, there was a significantly decreased tumor volume (219.7 ± 99.1 mm3) in mice receiving prophylactic CCR4 inhibition compared to vehicle controls (556.4 ± 351.8 mm3) (p = 0.026)." (PMID 37371612, 2023). "Targeting of the CCR4-phospho-paxillin axis was sufficient to reduce tumor progression and neuro-affinity of cancer cells in vivo." (PMID 37607005, 2023). "A possible explanation for the low clinical efficacy of KW-0761 is the unexpected decrease in central memory CD8+ T cells, which also express CCR4 and have anti-tumor immunity." (PMID 37729184, 2023). "Mogamulizumab is a first-in-class monoclonal antibody that binds to C-C chemokine receptor 4 (CCR4), which is expressed on the surface of tumor cells in T-cell malignancies." (PMID 38274457, 2023). "Wildtype mice exposed to pharmacological CCR4 inhibition presented decreased macrophage numbers in tumor tissue compared to the tumors of control mice." (PMID 37371612, 2023). "Simultaneous administration of an anti-PD-1 antibody, nivolumab, with a Treg-depleting anti-CCR4 mAb, mogamulizumab, provides an acceptable safety profile, anti-tumour activity, and a potentially effective option in cancer immunotherapy." (PMID 36980527, 2023). "The double-transduced T cells mimicked the behavior of one of the singular receptors in each organ: they resembled the pattern of CCR4 in the tumor and CCR7 in the draining lymph node." (PMID 37301772, 2023). "Inhibiting Treg infiltration into the tumor microenvironment using a CCR4 antagonist or N-CCR4-Fc effectively reduces Treg accumulation." (PMID 37576900, 2023). "The absolute number of Tregs was hardly decreased (CCR4−/−: 100 ± 21 FOXP3+ cells per 1 × 105 tumor cells vs. WT: 151 ± 29 FOXP3+ cells per 1 × 105 tumor cells; n = 9, p = 0.175), with a mean absolute reduction of 51 ± 36, (42.1%)." (PMID 37371612, 2023). "Targeting CCR4 was shown to be able to improve immunity by preventing Treg (CD4+) entry into the tumor microenvironment, and subsequently overcome sorafenib resistance." (PMID 37152990, 2023). "Cell-depleting anti-CCR4 mAb therapy is instrumental for evoking and enhancing tumor immunity in humans via selectively removing effector-type FOXP3+ Treg cells." (PMID 36839882, 2023). "We identified significantly improved tumor volume and survival outcomes in animals with genetic or pharmacological CCR4 suppression, which correlated with decreased intratumoral macrophage numbers." (PMID 37371612, 2023). "The aberrant overexpression of those ligands at the tumor site plays a central role in recruiting CCR4+ Th2 and regulatory T cells (Tregs) to such malignancies, resulting in an immunosuppressive TME." (PMID 35211124, 2022). "The terminally differentiated and most suppressive effector Treg cells predominantly express CCR4 in both cancer tissues and peripheral blood and anti-CCR4 mAb treatment selectively depletes effector Treg cells and induces anti-tumor immunity." (PMID 35222362, 2022). "We evaluated the expression level of CCR4 in both the peripheral circulation (source) and the tumor site (destination) since it is the tumor-specific migratory marker of Tregs." (PMID 35222362, 2022). "Moreover, recent studies have demonstrated that tumour-associated immunosuppressive ILC2s and myeloid derived suppressor cells (MDSCs) also express CCR4, prompting the need to investigate whether NK cells promote the recruitment of other immunosuppressive cells into the TME." (PMID 35565201, 2022). "Binding analysis revealed that the bivalent immunotoxin was more potent than its monovalent counterpart in recognizing human CCR4+ tumor cells and CCR4+ peripheral blood mononuclear cells (PBMCs)." (PMID 36158673, 2022). "CCR4 blockade inhibited the tumor growth and the infiltration of Tregs that prolonged the survival in a bladder cancer model." (PMID 35585567, 2022).
tumor (continued). "High CCR4 expression in the tumor microenvironment corresponds with high levels of Tregs, which can generate an immunosuppressive microenvironment and facilitate the immune escape of malignant cells." (PMID 36118530, 2022). "CCR4, which binds to macrophage-derived chemokine (MDC/CCL22) and thymus- and activation-regulated chemokine (TARC/CCL17), is predominantly expressed by tumor-associated Treg cells." (PMID 35222362, 2022). "Mogamulizumab, a defucosylated anti-CCR4 (chemokine receptor 4) antibody, was reportedly effective against some PTCLs that express CCR4 on tumor cells." (PMID 35954378, 2022). "Interference with FOXP3 binding to the CCR4 promoter reduces Treg infiltration in the tumor site, reactivating the suppressed anti-tumor immune response." (PMID 35222362, 2022). "Histological analysis of double-K/O tumors presented decreased tumor-associated CCR2 and CCR4 expression and poor macrophage-associated (F4/80+ cells) CCR2+ expression." (PMID 35980743, 2022). "In this respect, CCR8 represents a more tumor Treg cell-specific target than CCR4, which is known to be broadly expressed among blood and tissue Treg cells." (PMID 35158783, 2022). "Then mapping the expression of 10 GPCRs in the OS atlas, the results showed that CCR4 was mainly expressed in tumor-infiltrating lymphocytes (TILs), and its positive-cell proportion (PCP) in the tumor micro-environment was about 0.046%." (PMID 35463319, 2022). "On the other hand, CCR4 and MCP1 roles in Treg migration to the tumor have been shown through blocking CCR4/MCP1 in mice, which led to reduced frequency of infiltrating Tregs and inhibition of tumor growth." (PMID 36338731, 2022). "CCL17 and CCL22 were responsible for recruiting Treg into the tumor niche in a CCR4-dependent manner, leading to immune evasion and cancer metastasis." (PMID 36380313, 2022). "In a murine model of pancreatic cancer, the retroviral transduction of antigen-specific cytotoxic T cells with CCR4 enhanced migration to tumour sites and eliminated tumours in 40% of mice." (PMID 35205725, 2022). "Recently, it has been reported that tumor-infiltrating Tregs (TIL-Tregs) are predominantly CCR4+ and are functionally more immunosuppressive than those of CCR4-Tregs." (PMID 36613878, 2022). "CCR4 on activated effector Tregs is functionally related to chemical kinetic migration and is responsible for extending these cells to the tumor area." (PMID 35585567, 2022). "Despite the potential of targeting CCR4 for immunotherapies, exact role of CCR4 in Treg development, function and tumor-Treg crosstalk remains elusive." (PMID 36248808, 2022). "We intended to evaluate the status of CCR4 expression in other T-cell subsets (Th1 and Th2) because Tregs show a higher expression of CCR4 in tumor settings." (PMID 35222362, 2022). "Recruitment of Tregs to the TME occurs by binding of C-C chemokine receptor type 4 (CCR4) on the T cell surface by macrophage-derived chemokine (MDC/CCL22) produced by the tumor." (PMID 36092724, 2022). "Recently, a DT-based anti-CC chemokine receptor 4 (CCR4) immunotoxin showed considerable antiproliferative activity against human CCR4+ tumor cells." (PMID 36158673, 2022). "CCL22 released by tumor cells and tumor-infiltrating macrophages attracts the recruitment of Tregs through the combination of C–C chemokine receptor type 4 (CCR4)." (PMID 36119033, 2022). "Overexpression of FOXP3, on the other hand, increased CCR4+ Treg infiltration, resulting in a decreased anti-tumor immune response and tumor progression." (PMID 35222362, 2022). "Anti-CCR4 antibody treatment enhances antitumor immune responses mainly by altering tumor infiltrating Treg cells in an ovarian cancer model." (PMID 35359918, 2022). "The functional role of CCL22 in cancer immunity involves recruiting Tregs to the tumor stroma by binding to its cognate receptor CCR4." (PMID 35960749, 2022).
tumor (continued). "Double-labeling immunofluorescence confirmed that Foxp3+ Tregs expressed CCR4 in the tumor microenvironment." (PMID 35131860, 2022). "The decrease in tumor size is accompanied by a decrease in CCR4+ Treg generation both in the peripheral circulation and at the tumor site, demonstrating that FOXP3 transcriptionally activates CCR4 in both in vitro and in vivo settings." (PMID 35222362, 2022). "CCL17 and CCL22 are the ligands for CCR4, which effect on the recruitment of Treg, Th2, and Th17 into the tumor." (PMID 35517862, 2022). "Inhibition of CCR4 has been shown to reduce Treg cells accumulation, potentiate anti-tumour immune activity, sensitize tumours to PD-1 blockade and improve survival." (PMID 36569832, 2022). "In this study, we identified three tumor antigens, CCR4, TMCO1, and SPACA4, related to the prognosis and antigen-presenting cell infiltration of HNSCC." (PMID 36671475, 2022). "Our research identifies a FOXP3+ Treg population in tumor-infiltrating CD4+ lymphocytes that are largely CCR4+." (PMID 35222362, 2022). "Neutralization of the MCP-1/CCR2/CCR4 axis by knocking out CCR2/CCR4 recapitulates tumor growth and tumor landscape, as observed following pharmacological inhibition of MCP-1." (PMID 35980743, 2022). "We also established that TGFβ-induced FOXP3 enhances CCR4 transcription in Treg cells, making them amenable for tumor site infiltration." (PMID 35222362, 2022). "FOXP3 overexpression, on the other hand, enhanced tumor size by increasing the percentage of CCR4+ Tregs in the peripheral circulation as well as at the tumor site." (PMID 35222362, 2022). "Pharmacological antagonism of the CCR4 receptor with selective CCR4 antagonist, CCR4-35, effectively inhibited the recruitment of Tregs and resulted in enhanced anti-tumor efficacy, overcoming the immune resistance." (PMID 35585567, 2022). "Our finding of the phosphorylation-dependent adaptor function of DGKα revealed an important mechanism by which the CCR4/DGKα/FAK complex coordinately regulates CCL22-induced tumor metastasis." (PMID 35962191, 2022). "Chemokine ligands CCL17 and CCL22 present in TME facilitate the infiltration and accumulation of Tregs in tumor tissue through chemokine receptor 4 (CCR4), a G protein-coupled receptor, primarily expressed on the most immunosuppressive Tregs population." (PMID 36613878, 2022). "We show that the likelihood of CCR4 blockade therapy response (tumor burden reduction and survival) can be increased by determining the urinary CCL17 concentration or BRAFV595E somatic mutation." (PMID 35131860, 2022). "In two cases of tumor tissue collected before and after treatment, we confirmed that mogamulizumab reduced the number of Foxp3+ and CCR4+ cells." (PMID 35131860, 2022). "These CCR4+ tumor Tregs have been characterized as the most suppressive subset, allowing them to abundantly infiltrate tumor sites in multiple cancers such as gastric and esophageal cancers." (PMID 35345849, 2022). "Another potential problem is that approximately 20% of CD8+ tumor-infiltrating lymphocytes (TILs) express CCR4 in HNSCC patients." (PMID 36522365, 2022). "For tumor cell metastasis, the CCR4 antagonist reduced the lymph node metastasis more effectively than the CCL2 neutralizing antibody." (PMID 35177591, 2022). "Most CCR4+CD8+ T-cells are distributed along the periphery of the tumor nest, and some infiltrate the tumor nest." (PMID 36522365, 2022). "In HL-bearing humanized mice, chimeric defucosylated anti-CCR4 mAb (KM2760) dramatically boosted the number of tumor-infiltrating NK cells that mediate ADCC and decreased the number of tumor-infiltrating FOXP3-positive Treg cells." (PMID 35222362, 2022). "In the TME, CCL22 mediates Treg infiltration into the tumor tissue through CCR4, facilitating tumor immunosuppression and leading to inhibition of antitumor immunity." (PMID 35962191, 2022).
tumor (continued). "We did not identify a prognostic trend for FoxP3IM, possibly because cancer cells in the CT produce chemokines, such as CCL22 and CCR4, thus resulting in lower DC infiltration and recruitment of more FoxP3, and consequently favoring tumor growth." (PMID 33710816, 2021). "Tumor-infiltrating Treg cells in mice and humans predominantly express C-C chemokine receptor 4 (CCR4), which contributes to recruitment of Treg cells to tumors." (PMID 33748292, 2021). "To confirm the pivotal role of CCL2-CCR2 signaling in the communication between tumor cells and macrophages, we evaluated CCL2, CCR2, and CCR4 expression in the tumor." (PMID 34580284, 2021). "Like CTLA4 the chemokine receptor type 4 (CCR4), albeit being expressed on peripheral Tregs, is further upregulated on tumor-infiltrating Tregs, while additionally being expressed on different types of cancer cells." (PMID 33679808, 2021). "We have previously shown that vaccination with CCR4 antagonists also enhances CD8+ cytotoxic T cell (CTL) responses to the tumor antigens." (PMID 33669094, 2021). "In the tumor context, bone marrow chimera experiments in a model of murine glioma demonstrated the major role of CCR4 in the recruitment of Tregs in the brain TME to inhibit the antitumor immune response." (PMID 33924428, 2021). "The chemokine ligand 22 of the C-C motif (CCL22) is a member of the family of chemokines secreted by macrophages and tumor cells and binds to the chemokine [C-C motif] receptor 4 (CCR4)." (PMID 34452282, 2021). "CCR4 is expressed not only by type 2 helper T cells and regulatory T cells but also by tumor cells of MF, SS, and ATL." (PMID 34681738, 2021). "It is a high-affinity ligand of CCR4 and related to immunosuppression in the tumor microenvironment, especially by promoting the infiltration of regulatory T cells." (PMID 33819196, 2021). "Among them, CCR4 is the most well characterized trafficking receptor for Treg recruitment to the tumor microenvironment." (PMID 34885241, 2021). "So the mechanism of antitumor activity is that the mogamulizumab can reduce the number of CCR4-positive leukemic cells, boost antitumor immunity by reducing CCR4-positive Tregs and influence tumor microenvironment to reduce tumor escape." (PMID 34039310, 2021). "The chemokine ligand (CCL) 22 produced by macrophages and tumor cells can bind to chemokine receptor (CCR) 4 expressed on Tregs, consequently recruiting Treg into TME and leading to tumor growth and poor patients’ outcomes with its immunosuppressive function." (PMID 34062992, 2021). "CCL2 acts on CCR2 to advance the tumor, whereas, in CCR4, it acts to recruit cytotoxic T lymphocytes and exert an anticancer effect." (PMID 34445235, 2021). "CCR4 gene expression was significantly correlated with pathological tumor stage and T-stage (P<0.05)." (PMID 33692955, 2021). "A preclinical experiment has shown that mogamulizumab, which antagonizes CCR4, can reduce tumor lung metastasis, and a Phase III clinical trial has demonstrated that antibodies targeting CCR4 are effective in treating patients with cutaneous T lymphoma." (PMID 34977870, 2021). "Some of these signature genes (e.g., CTLA4, GITR, CCR4) are likewise present on peripheral Tregs, whereas their expression is increased in tumor-infiltrating Tregs." (PMID 33679808, 2021). "CCL17 and CCL22 induced by CD40 stimulation on B-cell leukemia cells have been shown to attract CCR4+ tumor-specific T cells." (PMID 33666760, 2021). "It has also been shown that CCR4-expressing Treg cells are recruited into tumor tissues by CCL22 that is produced in the tumor microenvironment by tumor cells and tumor-associated macrophages." (PMID 34771703, 2021). "Among them, CCR1, CCR2, CCR3, and CCR5 promote the recruitment of TAMs in the TME, and CCR4 mainly mediates the recruitment of Tregs, indicating that CC chemokines can be used as potential anti‐tumor pharmacological targets." (PMID 34977870, 2021).
tumor (continued). "Many more Th2 cells (CCR4+CD3+CD8-) than Th1 cells (CXCR3+CD3+CD8-) were detected in tumor stroma and in TLS by immunofluorescence." (PMID 34868011, 2021). "Pharmacological inhibition of BCL9 reduces tumor infiltration by Treg cells due to inhibition of CCR4 expression." (PMID 34417435, 2021). "Elimination of regulatory T cells via the anti-CCR4 monoclonal antibody, mogamulizumab, is expected to augment anti-tumour immune response." (PMID 34907192, 2021). "High levels of lactate in the TME promote differentiation of tumor-associated macrophages to the M2 subtype, while activated macrophages facilitate tumor invasion through the CCL17/CCR4/mTORC1 signaling axis." (PMID 35047511, 2021). "One animal study in canines confirmed that the expression of CCR4 was significantly higher in tumor tissues than in normal tissues and was significantly correlated with the content of Treg cells." (PMID 33692955, 2021). "By reducing the number of CCR4-positive Tregs and tumor cells, the mogamulizumab can reduce tumor burden and boost antitumor immunity to achieve antitumor effects." (PMID 34039310, 2021). "Conversely, blocking CCR4 in GH3 xenograft mice significantly inhibited tumor growth and the malignant biological properties of the tumors." (PMID 33664865, 2021). "The C-C chemokine receptor 4 (CCR4) in Treg cells plays a key role in tumor progression and metastasis." (PMID 34834282, 2021). "Increased Treg infiltration in the tumour microenvironment through C-C chemokine receptor 4 (CCR4) with the high expression level of the cytotoxic T-lymphocyte-associated protein 4 (CTLA-4) and PD-1 markers was linked with a poor prognosis in prostate cancer." (PMID 33924671, 2021). "In this regard, anti-CCR4 antibodies have been evaluated as a potential strategy to remove CCR4-expressing Tregs from the tumor microenvironment to enhance effector T cell function." (PMID 34796183, 2021). "Subsequently, these TAMs then secrete CCL17 to enhance tumor invasion via the CCL17/CCR4/mTORC1 axis." (PMID 33664865, 2021). "According to the results from TCGA-HNSC data set, compared to normal tissues, CCR4 exhibited a similar expression level in the tumor tissues (P>0.05)." (PMID 33692955, 2021). "For instance, CCL17 and CCL22, acting on CCR4, can directly recruit Th2 cells at the tumor site, thus participating in the development of cancers." (PMID 34777634, 2021). "Next, to investigate the effect of the CCL17/CCR4 axis on PA invasion in vivo, a tumor-bearing NOD/SCID mouse model was utilized." (PMID 33664865, 2021). "The group compared the efficacy of IL-2 fusion toxin with developed anti-human CCR4 immunotoxin (CCR4 IT) and demonstrated that CCR4 IT showed greater tumor response in a CD25 + CCR4 + CTCL mouse model than IL-2 fusion toxin." (PMID 33384022, 2020). "The CCR4 overexpression on CD30.CCR4.CAR-T cells aims to exploit this tumor physiology to allow for CD30.CCR4.CAR-T cells to better home to sites of disease." (PMID 33050054, 2020). "Treg cells express CCR4 and are recruited into the tumor micro environment in response to CCL22, which is produced mainly by macrophages and tumor cells." (PMID 33262763, 2020). "The ligands for CCR4 are produced by tumor cells or the microenvironment, and can attract CCR4-expressing T regulatory cells and create a good survive environment for tumor cells." (PMID 32429941, 2020). "In the CCR4‐IL2 IT group, no tumor cell areas were identified in the examined section of the liver, demonstrating that both the IL2‐CCR4 and CCR4‐IL2 bispecific ITs more effectively depleted the human CD25+CCR4+ tumor cells than IL2 fusion toxin or CCR4 IT." (PMID 32107846, 2020). "Infiltration of Tregs was caused by the interaction between the tumour-producing chemokine CCL17 and receptor CCR4 expressed on Tregs in dogs bearing spontaneous bladder cancer." (PMID 32680511, 2020). "The CCR4 IT group and the two bispecific IT groups demonstrated normal liver size with few sporadic tumor nodules." (PMID 32107846, 2020).